Y_RNA (Y RNA )
Gene: Miscellaneous RNA gene on chromosome 10 (110,642,678 to 110,642,785, reverse strand). Ensembl gene ENSG00000223302.
Homologues: Orthologues: chimpanzee Y_RNA (93% identical). Paralogues in human: Y_RNA (79% identical), RNY1P5 (78% identical), Y_RNA (78% identical), Y_RNA (77% identical), Y_RNA (76% identical), Y_RNA (75% identical), Y_RNA (74% identical), RNY1P2 (73% identical), Y_RNA (73% identical), RNY1 (72% identical), RNY1P1 (72% identical), RNY1P6 (72% identical), and 94 more.